GPX4 (glutathione peroxidase 4)
Diseases named in the same sentence as GPX4 in open-access papers (continued):
Sharing a sentence is not in itself a finding about the gene and the disease.
tumor (continued). "Previous studies have shown that GPX4 is highly expressed in metastatic cancers and is closely related to tumor progression." (PMID 36369321, 2023). "FIN56 is another novel inhibitor of GPX4 that promotes GPX4 degradation and induces tumor ferroptosis." (PMID 38020609, 2023). "We used the ssGSEA algorithm to estimate the abundance of Tumor-Infiltrating Immune Cells (TIICs) in the TME, and the results demonstrated GPX4 was positively associated with most TIICs in patients with COAD." (PMID 38065948, 2023). "It was also reported that selenoprotein is upregulated in tumor, which suggests the enhanced expression level of GPX4 in the development of tumor." (PMID 37229485, 2023). "Inspired by the accidental discoveries, we constructed a NK-92 cell strain with high expression of GPX4 and treated the humanized xenograft tumor mice model with the NK-92 cells." (PMID 36855135, 2023). "In conclusion, viruses downregulate System Xc− and GPX4 during infection through epigenetic or anti-oncogene regulation, leading to ferroptosis in infected cells, which promotes viral release or againsts tumor cells." (PMID 38140616, 2023). "This review explored the structure and function of GPX4, with the overarching goal of revealing its mechanism and potential application in tumor therapy through regulating ferroptosis." (PMID 36675129, 2023). "This eventually results in the inhibition of the SLC7A11/GPX4 axis and the promotion of ferroptosis in various tumor cells." (PMID 38081931, 2023). "Together, these results suggested a positive correlation between NeuroD1 and GPX4 in tumor tissues, further confirming the possible regulation of NeuroD1 on GPX4 as obtained by cellular experiments." (PMID 38134213, 2023). "The results showed that the expression of GPX4 in tumor tissues was upregulated compared to in peritumor tissues (P < 0.05)." (PMID 37554285, 2023). "Knocking down NeuroD1 clearly suppressed the tumor growth rate, as shown by the changes in tumor volume, while overexpressing GPX4 restored it." (PMID 38134213, 2023). "Several studies have shown that GPX4 participates in carcinogenesis and plays a critical role in tumor growth, metastasis, and drug resistance (Hassannia, Vandenabeele & Berghe, 2019)." (PMID 36632137, 2023). "IHC staining validated the much lower expression of KI‐67, Fibronectin, GPX4, and Nrf2 in tumor samples from the OXA/sh‐FOXA2 group of mice, which was comparable with the OXA and sh‐FOXA2 single treatment groups." (PMID 37875418, 2023). "Like GPx1-3, GPx4 is also a tumor suppressor due to its down-regulation in breast cancer and pancreatic cancer." (PMID 38202704, 2023). "Currently, there are many drugs for tumor ferroptosis, and most of them inhibit system xc−and GPX4 to promote ferroptosis." (PMID 37005430, 2023). "The current emerging nano therapies mainly focus on inhibiting the expression of GPX4 in tumor cells, increasing the accumulation of ferrous/iron ions in tumor cells, and regulating lipid peroxidation." (PMID 37996827, 2023). "Consistent with those within the in-vitro experiments, knockdown of COL12A1 in GC cells reduced the tumor mass growth and decreased the expression of GPX4 and SLC7A11 in xenograft models." (PMID 37700383, 2023). "GPX4 protein expression, assessed by Western blot on isolated tumor cells and IHC of tumors, was significantly lower in KPV−/− cells than in KPV+/+ cells and in tumors from WFA-treated KPV+/+ mice compared to vehicle control." (PMID 37161053, 2023). "A systematic study performed on miR-1287-5p revealed that it directly binds to the 3′ UTR of GPX4 to suppress its protein activity, since the overexpression of GPX4 entirely stops miR-1287-5p-induced ferroptosis and tumor suppression." (PMID 37240889, 2023). "Patients with advanced RCC were divided into two groups (high vs. low expression) according to the median expression of FAAH and GPX4 in tumor tissue and then followed clinically." (PMID 37024452, 2023).
tumor (continued). "By regulating the expression of GPX4, the accumulation of peroxides in tumor cells can be controlled, and ferroptosis can be regulated." (PMID 36910646, 2023). "Immunoblotting results revealed significantly reduced GPx4 levels in the tumor tissues of SKOV3-bearing mice models compared to those in vehicle-treated groups, with no change in the levels of other selenium proteins." (PMID 36768241, 2023). "Ce6-PDT can induce DNA damage response, and then up-regulate the expression of GPX4, leading to the resistance of tumor cells to PDT." (PMID 37894410, 2023). "SLC7A11 and GPX4, which are upregulated in tumor cells, serve to protect them from ferroptosis induced by irradiation." (PMID 37980334, 2023). "This is most obvious in epithelial-derived carcinomas in which tumor cells have been fixed in a therapy-resistant mesenchymal state which clearly relies on GPx4 expression." (PMID 37373256, 2023). "Growing investigations have found that NF-κB signaling can modulate Gpx4-mediated ferroptosis in tumor cells." (PMID 38034017, 2023). "Studies have further found EBV infection has a vital impact on redox homeostasis, revealing the role of GPX4 in tumor progression and providing a latent novel target for the therapy of EBV-related cancers." (PMID 36845720, 2023). "Meanwhile, multiple oncoproteins and tumor suppressors promote this phenomenon and iron death proteins such as GPX4, ACSL4 and PTGS2 can be utilized in anti-tumor." (PMID 37542283, 2023). "It inhibits GPX4, leading to tumor-specific ferroptosis, and TA is used to chemically reduce Fe3+ to Fe2+ and continuously supply Fe2+ to maintain the iron redox cycle and maintain the Fenton reaction." (PMID 37996827, 2023). "We also found that the mRNAs of CD86 and BTNL8 were expressed in the siGPX4 group, suggesting that knocking down GPX4 increased T-cell activity and killed tumor cells." (PMID 37649598, 2023). "The second-generation antiandrogens combined with ferroptosis activators can further inhibit tumor proliferation by inhibiting the expression of GPX4." (PMID 36056183, 2023). "Recently, CHAC1 and NOX4, along with GPX4, have been suggested to be hallmarks of ferroptosis in tumor cells." (PMID 37371096, 2023). "A total analysis of pan‐cancer patients revealed higher expression level of GPX4 in tumor tissues than in normal tissues." (PMID 37229485, 2023). "Taken together, these findings suggest that inhibition of both Lp-PLA2 and GPX4 synergistically inhibits tumour growth in vivo." (PMID 37714840, 2023). "These in vitro observations were also fully supported by in vivo experiments on tumor xenografts built from GPx4-wild type and GPx4 knock-out clones of such cells." (PMID 37373256, 2023). "In the future, co-targeting CAIX/XII activity in combination with ferroptosis inducers, such as inhibitors of GPX4, have the potential to achieve substantial in-roads in treating hypoxic tumours, especially those exhibiting chemo- and radio-resistance." (PMID 38099193, 2023). "Several small-molecule compounds exhibit anti-tumor effects through ferroptosis, including sorafenib and altretamine, which induce ferroptosis by inhibiting System-Xc and GPX4 respectively, but many problems, such as poor druggability, still exist." (PMID 37833746, 2023). "Silencing GPX4 in combination with gefitinib treatment reduced tumor growth and decreased ROS in tumor xenografts." (PMID 37779896, 2023). "In accordance with these results, the IHC staining demonstrated a reduced intensity of the proliferation marker Ki67 in GPX4 knockdown tumor lesions." (PMID 35105963, 2022). "Under the acidic environments of lysosomes, Ir(III) can effectively catalyze a Fenton-like reaction, produce hydroxyl radicals, induce lipid peroxidation, down-regulate GPX4, resulting in ferroptosis, and thus inhibit tumor cell growth." (PMID 36710875, 2022).
tumor (continued). "Quantitative polymerase chain reactionanalysis of the mRNA expression in U-87 MG and SKOV-3 tumor tissuesfrom 15-treated mice showed the presence of Ptgs2/Nfe2l2/Sat1/Akr1c1/Gpx4 genes correlated with ferroptosis in bothgroups." (PMID 36395526, 2022). "Western blot results indicated that the expression level of GPX4 protein in EC tumor tissue was significantly higher than that in normal endometrium." (PMID 35962333, 2022). "These in vitro findings corroborate the patient tumor tissue data demonstrating GPX4 overexpression in 45% of patients with PTC." (PMID 36371529, 2022). "GPX4, which is a negative regulator of ferroptosis, knockdown can enhance tumor cell oncogenic and metastatic activity." (PMID 36177184, 2022). "GPX4 is an important regulator of ferroptosis and functions as a carcinogen by impeding ferroptosis in tumor cells." (PMID 35620733, 2022). "These released Fe2+ ions triggered ferroptosis in the tumor, showing hallmarks of lipid peroxidation and GPX4 depletion." (PMID 35473696, 2022). "The discovery of various enzymes regulating ferroptosis has enabled the targeted therapy of tumors, the most prominent target being GPX4, which is expressed in most tumor cells and is important for cell survival." (PMID 36425577, 2022). "The GPX4 inhibitor not only suppress the proliferation but also reshape the tumor microenvironment of LAR subtype." (PMID 36467032, 2022). "The OS and the histological expressions of PRKACA and GPX4 in normal and tumor tissues were exhibited, in accordance with the results front." (PMID 35646872, 2022). "In other words, GPX4-expressing tumor cells are likely to acquire the ability to detoxify ROS, and be resistant to therapy." (PMID 36443446, 2022). "Taken together, our findings suggest that EBV infection has important effects on redox homeostasis, revealing a previously unappreciated role for GPX4 in tumor progression." (PMID 35105963, 2022). "Further analyses of the TCGA and GEO database revealed that GPX4 expression was significantly upregulated in tumor tissues compared with their normal counterparts." (PMID 35534546, 2022). "Anaesthetic drugs protect against ferroptosis or promote tumour cell ferroptosis through the System xc-/GPX4 pathways, iron metabolism, lipid metabolism and other pathways." (PMID 36313359, 2022). "The Fenton reaction, NADPH-dependent lipid peroxidation, GSH depletion, and decreased GPX4 activity can all promote ROS accumulation in tumor cells, which induces ferroptosis in tumor cells." (PMID 36185243, 2022). "In tumor cells with low GPX4 expression, DHODH activity is significantly reduced or even inactivated, which gives rise to mitochondrial lipid peroxidation accumulation and activates ferroptosis, thereby inhibiting tumor growth." (PMID 35911967, 2022). "The findings also suggest that adjusting the expression level of GPX4 and cysteine can effectively prevent and treat tumor diseases, adjusting the expression level of GPX4 and cysteine using iron treatment promotes ferroptosis leading to tumor death." (PMID 35844870, 2022). "The study found that silencing of NF2 activates ferroptosis-related pathways in GPX4-knockout tumor mice." (PMID 35911967, 2022). "Firstly, several studies have shown that inhibiting the expression of GPX4 gene can effectively kill tumor cells through ferroptosis." (PMID 35252001, 2022). "The over-loaded Fe2+ ions in the tumor cells then triggered ferroptosis, with hallmarks of lipid peroxidation and cellular glutathione peroxidase 4 (GPX4) down-regulation." (PMID 35473696, 2022). "At the same time, acrolein can activate carbonyl stress reaction in tumor cells and inhibit the expression of GPX4 and DNA repair protein, leading to severe lipid peroxidation and DNA damage, and finally cause the death of tumor cells." (PMID 36559134, 2022).
tumor (continued). "They found that AMSNs have highly efficient glutathione depletion capabilities and subsequently leads to ferroptosis by inactivating GPX4, which provide important insights for tumor targeting with nanomedicines." (PMID 36033530, 2022). "GPX4 content is a key factor in tumor ferroptosis, and these microRNAs have been shown to promote ferroptosis in various tumor cells by inhibiting target genes involved in GPX4 synthesis." (PMID 36310600, 2022). "The results showed that the expression of GPX4 in EC tumor tissues was significantly elevated than that in normal endometrial tissues (P < 0.05)." (PMID 35962333, 2022). "Changes in the protein content in transplanted tumor tissues were detected, and the expression of GPX4, xCT and MTTP was decreased in the L‐OHP injection group, which was reversed by treatment with adipocyte exosomes." (PMID 35978266, 2022). "The specific DHODH inhibitor brequinar selectively suppresses cancer cells with low expression of GPX4 induced tumor growth." (PMID 35882850, 2022). "Especially tumor cells rely on enzymes like GPX4 to prevent oxidative stress and assure their survival by therapy resistance." (PMID 35530303, 2022). "A number of studies have shown that inhibiting SLC7A11, GPX4 or other ferroptosis related molecules can reduce the production of glutathione, thereby promoting tumor cell ferroptosis and suppressing tumor growth and metastasis." (PMID 35579738, 2022). "qRT-PCR analysis of isolated tumor tissues from implanted mice showed that Arg2 mRNA expression was significantly inhibited, accompanied by a decrease in GPX4 level." (PMID 36604146, 2022). "In multivariate analyses, only age, surgical resection, tumor grade, “T”, “N”, and GPX4 expression remained significant prognostic factors for OS with GPX4 cutoff value at both 5% and 25%." (PMID 36443446, 2022). "Tumours are resistant to ferroptosis agonists that inhibit GPX4, which suggests that there seem to be other ways that ferroptosis occurs." (PMID 36309489, 2022). "In the xenograft model, we confirmed that inhibition of glutathione peroxidase 4 restrained tumor regrowth after discontinuation of anti-cancer drug treatment." (PMID 35719967, 2022). "Western blotting of tumor tissues showed that the expression levels of GPX4 and SLC7A11 were downregulated after treatment with apatinib." (PMID 35602105, 2022). "Some studies have shown that the expression level of GPX4 in tumor tissues is significantly higher than that in normal tissues, such as renal clear cell carcinoma, lung adenocarcinoma, prostate cancer, thyroid cancer, and gastric cancer." (PMID 35962333, 2022). "Then, expressions of OTUB1, SLC7A11 and GPX4 in tumor (n=179) and normal (n=171) tissues as well as their associations with survival outcomes were evaluated." (PMID 35494004, 2022). "In GBM cells, high GSH/GPX4 levels induce epithelial-mesenchymal transition, leading to tumor progression, metastasis and chemoresistance." (PMID 36072803, 2022). "We further found that ferroptosis was involved in the process of tumor cell death, in which ferroptosis marker GPX4 was significantly decreased and ACSL4 was significantly increased." (PMID 35366904, 2022). "Consistent with PSTK knockout, Punicalin or Geraniin treatment induced significant decreases in GPX4 protein levels in these tumor cells." (PMID 34983546, 2022). "At present, ferroptosis inducers used in clinical tumor treatment primarily inhibit the activity of System XC- and GPX4." (PMID 35688814, 2022). "GPX4 knockdown dramatically alleviated subcutaneous tumor burden and diminished tumor growth over time compared to the control." (PMID 35105963, 2022).
tumor (continued). "Growing evidence suggests that when GPX4 is inactivated, FSP1 can continue to maintain tumor growth in vivo, while deletion of GPX4 and FSP1 can inhibit tumor growth." (PMID 36425577, 2022). "The results of this study displayed a significant reduction in xenograft tumor size and a decrease in the expression of Glutathione peroxidase 4 (GPX4) and Nrf2." (PMID 36289931, 2022). "While mTORC1 is a key signaling node that integrates multiple environmental signals to modulate protein (e.g., GPX4) synthesis, and its inactivation reduces GPX4 and sensitizes tumor cells to ferroptosis." (PMID 36105219, 2022). "FSP1 maintains the lung tumor growth of GPX4 knockout H460 cells in tumor xenograft mouse models under the treatment of IKE (System Xc- inhibitor and ferroptosis inducer in vivo)." (PMID 35882850, 2022). "We scored the GPX4 expression level based on the GPX4 staining intensity and the percentage of positive tumor cells." (PMID 35962333, 2022). "Several tumor cell lines are resistant to ferroptosis inducers, even when the ferroptosis key enzyme glutathione peroxidase 4 (GPX4) is blocked, indicating that other important elements are also involved in this process." (PMID 35402247, 2022). "The researchers suggested that IR also induces adaptive responses involving SLC7A11 or GPX4 induction to promote tumor cell survival during radiotherapy, which is one of the reasons for radioresistance." (PMID 36072803, 2022). "These drug resistant tumor cells protect themselves from death threats including ferroptosis inducers through many mechanisms including System Xc−/GSH/GPX4 axis." (PMID 36105219, 2022). "Studies clearly show that the inhibitor of GPX4 induces ferroptosis in not only cultured cancer cells but also tumor xenografts implanted in mice." (PMID 36203872, 2022). "The study has revealed that GPX4 is upregulated across cancers and has the function of promoting the tumor progression." (PMID 35309514, 2022). "Ferroptosis is triggered in tumor cells by cysteine (Cys) depletion or by inhibition of glutathione peroxidase 4 (GPX4)." (PMID 36185243, 2022). "Although ferroptosis is rare in T-reg cells, recent studies have shown that targeting GPX4 can disturb the immune homeostasis, promote the production of IL-1β and Th17 cell reaction, thus enhancing the anti-tumor immune function." (PMID 36387286, 2022). "Taken together, we provide in vivo evidence that demonstrates the role of TCF4 in promoting GPX4 expression, which results in the decrease of lipid peroxidation levels in tumors and facilitates tumor growth." (PMID 35534546, 2022). "GPX4 overexpression has been described in many aggressive cancers, making it a potential therapeutic target able to promote death in drug-tolerant tumor cells." (PMID 35872783, 2022). "Our work aimed to determine the possible involvement of glutathione peroxidases 4 and 8 (GPx4 and GPx8) in this specific tumor process." (PMID 35208621, 2022). "In this sense, destroying the enzymatic activity of GPX4 is a promising manner to amplify ferroptosis in tumor cells." (PMID 39070608, 2022). "It was found that the expression of GPX4 in EC tumor tissues was higher than that in normal endometrial tissues (P < 0.05)." (PMID 35962333, 2022). "The strategy of this therapy is mainly to directly deliver nano-drugs with GPX4-inhibiting function to the tumor cell or inhibit GPX4 activity by efficiently removing GSH or blocking its synthesis." (PMID 36274142, 2022). "Changes in the protein content in transplanted tumor tissues were detected, and the expression of GPX4, xCT and MTTP was decreased in the KD‐MTTP group." (PMID 35978266, 2022). "While the expression of GPX4 decreased significantly during tumor relapse, ACSL4 showed a significant increase." (PMID 35530303, 2022).